MTOR (mechanistic target of rapamycin kinase)
Diseases named in the same sentence as MTOR in open-access papers (continued):
Sharing a sentence is not in itself a finding about the gene and the disease.
breast cancer (continued). "In addition, PL induced apoptosis of breast cancer cells via activation of transcription 3 (STAT3) and phosphatidylinositol 3-kinase (PI3K)/Akt/mammalian target of the rapamycin (mTOR) signaling pathway." (PMID 31739520, 2019). "To gain insights into the activity of Akt and ERK after PI3K/mTOR signaling inhibition by B591, we further analyzed the time-course phosphorylation of Akt and ERK after incubation of rhabdomyosarcoma RD cells and human breast cancer MDA-MB-231 cells with B591." (PMID 30635656, 2019). "Moreover, pharmacological FGFR4 inhibition specifically sensitized the HER2+ MDA-MB-453 breast cancer cells, not only to HER2/EGFR and AKT/mTOR inhibitors, but also to clinically relevant apoptosis modulators." (PMID 30903103, 2019). "The third generation, bivalent mTOR inhibitor, RapaLink, inhibits breast cancer cell growth at a level comparable to rapamycin, is effective against hyperactive mTOR-mutant cells and did not allow the evolution of resistance during the course of the study." (PMID 35582282, 2019). "A recent study examining PIK3CA-mutant breast cancers showed that heightened PI3K-mTOR signaling is a key driver of Mcl-1 overexpression in these tumor cells, and that PI3K/mTOR inhibition impaired Mcl-1 expression, increasing PIK3CA-mutant cell sensitivity to ABT-263." (PMID 31595181, 2019). "Based on clinical trials, mTOR inhibition in combination with an endocrine therapy is a new therapeutic strategy for women with advanced breast cancer who have previously relapsed on a non-steroidal aromatase inhibitor." (PMID 31428575, 2019). "For example, next generation sequencing analysis of a liquid biopsy from a patient with advanced breast cancer, who failed to respond to conventional chemotherapy, showed mutations in PIK3CA, PTEN and mTOR." (PMID 35582282, 2019). "Although inhibitory or activating effects of arsenite on mTOR have been reported, we found in MCF-7 breast cancer cells that arsenite stress activated mTORC1, as monitored by the phosphorylation of p70-S6K at threonine 389 (p70-S6K-T389) and 4E-BP1 at threonine 37/46 (4E-BP1-pT37/46)." (PMID 30923191, 2019). "Our recent studies found that Aur-A activates mammalian target of rapamycin (mTOR) pathway in breast cancer cell models and inhibits autophagy activity, which is not dependent on the classical PI3K-AKT1 pathway." (PMID 31406104, 2019). "As ITM2A is downregulated in breast cancer, the inhibitory effect of ITM2A to mTOR could be abolished." (PMID 31438969, 2019). "In addition to breast cancer, the synergistic anti-tumor effect of dual inhibition of the PI3K/AKT/mTOR pathway and CDK4/6 has also been demonstrated in malignant pleural mesothelioma, T-cell acute lymphoblastic leukemia, and mantle cell lymphomas." (PMID 31101835, 2019). "Previous studies revealed that mTOR, HOXA1, and IGFBP1 were targeted by miR-99a in breast cancer; FGFR3 was targeted by miR-99a in bladder cancer; in the present study, we identified FGFR3 as a direct target of miR-99a in breast cancer for the first time." (PMID 32038996, 2019). "in conclusion, our data show that pAKT and p-mTOR pathway activation have differing impact on prognosis and suggest that they are not linearly connected in luminal breast cancers." (PMID 30729154, 2019). "The same anti-apoptotic effect has been reported in breast cancer, where ERK1/2 cooperates with 5′ AMP-activated protein kinase/mammalian target of rapamycin/p70 S6 kinase (AMPK/mTOR/p70S6K), and in colorectal cancer, where it cooperates with small mothers against decapentaplegic-4 (Smad4)." (PMID 31117237, 2019). "Furthermore, it was proven that honokiol was able to attenuate PI3K/Akt/mTOR signalling via the down-regulation of Akt phosphorylation and upregulation of PTEN expression in breast cancer cells (MCF-7, MCF-7/adr, and BT-474 cell lines)." (PMID 31877856, 2019).
breast cancer (continued). "Protective autophagy was induced over a range of treatment doses and was enhanced by an increase in the dose of delphinidin via suppression of the AKT/mTOR/eIF4e/p70s6k signalling pathway and activation of the LKB1/AMPK/ULK1/FOXO3a signalling pathway in HER-2 positive breast cancer cells." (PMID 29587684, 2018). "Next, we estimated the sensitivity of BC5, BrCCh1, and BN1 breast cells to various chemotherapeutic agents: doxorubicin, cisplatin, tamoxifen, anastrozole, and the mTOR-inhibitor afinitor (everolimus), which is used for treatment of advanced hormone receptor-positive, HER2-negative breast cancer." (PMID 29986702, 2018). "In our study, we found that AITC upregulated mTOR expression, indicating AITC may promote breast cancer progression." (PMID 29300316, 2018). "Researchers showed that MET reduced migration and invasion of cancer cells in tamoxifen-resistant breast cancer cells and in combination with tamoxifen synergistically inhibited proliferation of ER-positive breast cancer via Bax/Bcl-2 and AMPK/mTOR/p70S6K pathways." (PMID 30483391, 2018). "In this study, we found that IKKβ not only acts directly on mammalian target of rapamycin (mTOR) activity but also indirectly acts on mTOR activity through posttranscriptional modification of ARD1, thereby effectively promoting the growth of breast cancer cells." (PMID 30154412, 2018). "In addition, delphinidin induced autophagy via suppression of the mTOR signalling pathway and activation of the AMPK signalling pathway in HER-2 positive breast cancer cells." (PMID 29587684, 2018). "Moreover, silencing of TM4SF1 suppressed breast cancer cell migration and invasion and induced apoptosis via inhibition of p-AKT/p-mTOR pathway." (PMID 30135139, 2018). "On the contrary, PRDX1 has a tumor promoting role in breast cancer, bladder cancer, oral squamous cell carcinoma, lung cancer, and esophageal squamous cell carcinoma through activation of NF-κB pathway, FOXO1-mediated pathway, and mTOR/p70S6K pathway." (PMID 30104402, 2018). "Although mutations in PIK3CA are common in breast cancer, they have not been reliably predictive of clinical response to drugs targeting the PI3K/mTOR pathway." (PMID 29177603, 2018). "As PI3K-Akt-mTOR signaling relate to proliferation, and tumor growth and invasion is a major effector of HER2 activity, the blockade of the PI3K signaling pathway by trastuzumab suppresses tumor growth in multiple models of HER2-overexpressing breast cancer." (PMID 29482416, 2018). "Similarly, 7-chloro-fascaplysin inhibited cell survival through interference with the PI3K/Akt/mTOR pathway, which in turn modulates HIF-1α, eNOS and MMP-2/9 in a breast cancer cell line." (PMID 30322180, 2018). "Apart from that, PI3K was shown as target to sensitize breast cancer cells for adriamycin toxicity and the combined PI3K/mTOR inhibitor BEZ235, that we also used here, was shown to sensitize genetically modified CDDP resistant breast cancer cells for cytotoxicity in a recent study." (PMID 30563275, 2018). "Furthermore, our studies indicate that SALL1 expression in breast cancer selectively utilizes both MAPK and mTOR signaling pathways controlling tumor cell fate and functions." (PMID 29625565, 2018). "Additionally, we previously demonstrated that PA inhibits the invasion of breast cancer cells through the NF-κB, MAPK, and mTOR signaling pathways." (PMID 30177595, 2018). "Different breast cancer subtypes have different, unique PI3K/AKT/mTOR signaling pathway changes, which may result in different clinical manifestations, so a molecular characterization of each tumor subtype is required to develop a unique treatment therapy." (PMID 29614812, 2018).
breast cancer (continued). "Interestingly, metformin decreased radio-resistance of CSCs in mouse fibrosarcoma cells and human MCF7 breast cancer cells by activating AMP-activated protein kinase and suppressing mTOR expression." (PMID 29385093, 2018). "In our study, adjustment for ER status did not materially change the results and adjustment for breast cancer subtype led to slightly stronger associations of insulin with IGF1R and p-mTOR." (PMID 29486734, 2018). "Reciprocally, OGT silencing or inhibition increases phosphorylation of AMPK, decreases phosphorylation of mTOR downstream effectors 4E-BP1 and p70S6K, decreases HIF-1a, GLUT1, and LDHA expression and impairs glucose uptake and growth in breast cancer cell lines." (PMID 30356686, 2018). "Moreover, combination of PI3K/mTOR and BET inhibitors drives complete cell kill of basal-like breast cancer cell lines (BCCLs) in vitro, and tumor regression of orthotopic xenografts in vivo." (PMID 30232459, 2018). "In breast cancer specifically, FBW7 was reported to target mTOR for proteasomal degradation." (PMID 28036276, 2017). "As CPT could block ERα‐mediated IGF‐1/AKT/mTOR pathway, it needs to be clarified whether CPT could inhibit tamoxifen‐resistant breast cancer." (PMID 28272775, 2017). "Finally, its role on crosstalk between ERα and IGF‐1/AKT/mTOR pathway was confirmed, convincing us that CPT should be a potential agent for prospective application in a tamoxifen‐resistant breast cancer." (PMID 28272775, 2017). "The mammalian target of rapamycin (mTOR) is a key component of the PI3K-Akt-mTOR pathway, which has recently been considered to play a critical role in tumor escape from hormone dependence in breast cancer." (PMID 27765921, 2017). "Therefore, novel therapeutic approaches to overcome primary and secondary resistance to trastuzumab include inhibition of angiogenesis and other signaling pathways (PI3K/mTOR, IGF1-R, HSP90) involved in breast cancer growth." (PMID 28533703, 2017). "In summary, considering that a major part of human breast cancers have activation of PI3K/Akt/mTOR pathway, targeting Akt and mTOR together in the treatment of this disease may enhance antitumor efficacy." (PMID 28991258, 2017). "In summary, our findings demonstrate that the simultaneous suppression of the combination of the PI3K/mTOR inhibitor BEZ235 and the pan-HDAC inhibitor TSA is more effective than single agent in inhibiting the viability of breast cancer cells in vitro and tumour progression in vivo." (PMID 28060760, 2017). "While in breast cancer, there are no clinical studies assessing the immunoregulatory effects of mTOR inhibitors." (PMID 29070044, 2017). "The anticancer activities of baicalein have been attributed to a variety of mechanisms that are important in breast cancer, including inhibiting 12-LOX activity, upregulating DDIT4 expression, inhibiting mTOR, and suppressing the aromatase (CYP19) activity and thus decreasing estrogen biosynthesis." (PMID 28060756, 2017). "Given the critical role of mTOR in negatively regulating autophagy, we then studied whether co-treatment with BEZ235 and TSA induce autophagy in breast cancer cells." (PMID 28060760, 2017). "In the present work we assessed the influence of doxorubicin treatment on PTEN and Akt-mTOR-S6K signaling, and the interaction between doxorubicin and the Akt inhibitor A-443654 in ER positive and negative human breast cancer cell lines in vitro and in vivo." (PMID 28476032, 2017). "We measured the changes in global translation in cells subjected to hypoxia or to hypoxia plus an mTOR inhibitor, comparing non-tumoural versus tumoural human breast cancer cell lines." (PMID 29383126, 2017). "Additionally, we observed that BME treatment in breast cancer cells increases phospho-AMPK expression and inhibits the mTOR/Akt signaling pathway." (PMID 29029506, 2017).
breast cancer (continued). "In contrast, although we found that CCL5-CCR5 axis played an essential role in the metabolic communication between macrophages and breast cancer cells, we did not observed the activation of mTOR signaling in the co-culture system (data not shown)." (PMID 29299159, 2017). "We present here a metabolomic investigation exploring the impact of mTOR inhibition on serum metabolic profiles from patients with non-metastatic breast cancer overexpressing HER-2." (PMID 29137365, 2017). "Immunofluorescent staining of tumour sections from human oestrogen receptor (ER)-negative breast cancer patients showed a strong correlation between phosphorylated P70S6 kinase (mTOR downstream target), VEGF and SK1 protein expression." (PMID 28615679, 2017). "We confirmed potent inhibition of several off-targets and were keen on reducing the inhibition of FRAP1(mTOR), PIK3CA, and CDK7, as these kinases drive proliferation in breast cancer, which would complicate the interpretation of MELK-dependent pharmacology if inhibited." (PMID 28926338, 2017). "Aberrant PI3K/Akt/mTOR signaling is also seen in cells with FGFR1 overexpression and amplification, and response to the PI3K inhibitor alpelisib is reduced in ER+/PIK3CA-mutant breast cancer cells that overexpress FGFR1." (PMID 28183331, 2017). "CK2 could act through several signaling pathways and mechanisms in breast cancer such as NF-κB, JAK/STAT, MAPK, Akt/MTOR, SIRT6, and miRNA expression." (PMID 28134850, 2017). "Our findings suggested that p-mTOR overexpression was not significantly related to prognosis in breast carcinoma regarding OS and disease recurrence." (PMID 28114374, 2017). "In conclusion, compared with low p-mTOR expression, p-mTOR overexpression was not significantly related to the prognosis of breast carcinoma patients regarding OS and disease recurrence." (PMID 28114374, 2017). "It is thus possible that, like mTOR, PLK1 may also mediate the effect of miR-100 on breast cancer sensitivity to paclitaxel, though this remains to be determined." (PMID 26744318, 2016). "The lead compound, 2-chloro-3-(4, 5-diphenyl-1H-imidazol-2-yl) pyridine (CIP) suppressed the proliferation of breast cancer cells, decreased the phosphorylation of PDK, Akt, mTOR, downregulated the cellular invasion and activated caspases and cleaved PARP to induce apoptosis." (PMID 27097161, 2016). "In the SP of MCF-7 breast cancer cells, activation of the PI3K/mammalian target rapamycin (mTOR) signaling pathway was important for tumorigenecity of these CSCs, and knockdown of PI3K or mTOR led to ablated tumorigenecity." (PMID 26682001, 2016). "Moreover, a dynamic interplay between IGF and ERα in breast cancer cells has been demonstrated, where IGF-1R increase ERα phosphorylation and activity via mTOR/S6K1 and ERα mediates IGF-1R, IRS-1 and IGF ligand expression." (PMID 27765027, 2016). "To determine the response of these PDX models to an mTOR inhibitor, we treated them with everolimus as single agent, given at 2.5 mg/kg 3/week, a dose well tolerated and highly efficient in PDX models of ER+ breast cancer." (PMID 27374081, 2016). "In this study, clinical samples treated prospectively together with in vitro functional studies concordantly show simvastatin to induce apoptosis, suppress proliferation and dephosphorylate sequential signalling cascades of PI3K/Akt/mTOR and MAPK/ERK pathways of breast cancer." (PMID 26565813, 2016). "Most natural polyphenols are thought to impair breast cancer metastasis through downregulation of MMPs expression, interference with the VEGF signaling pathway, modulation of EMT regulator, inhibition of NF-κB and mTOR expression, and other related mechanisms." (PMID 27999314, 2016).
breast cancer (continued). "Since mTOR pathway is a key regulator of cell growth and proliferation, its deregulation might be an important clue for FADD function in breast cancer." (PMID 27013580, 2016). "We and others found that total mTOR protein level is elevated in breast cancer cells compared to their nonmalignant counterparts." (PMID 27748082, 2016). "To functionally evaluate whether mTOR plays a role in miR-100-mediated paclitaxel sensitization, we treated MCF-7 breast cancer cells with a concentration of paclitaxel (1 ng/ml) that was too low to affect cell proliferation and survival." (PMID 26744318, 2016). "In the case of the insulin-like growth factor (IGF) pathway, the mTOR complex (mTORC1) mediates IGF-1 receptor (IGF-1R)-induced estrogen receptor alpha (ERα) phosphorylation/activation and leads to increased proliferation and growth in breast cancer cells." (PMID 27765027, 2016). "Everolimus and other PI3K/Akt/mTOR inhibitors are known to induce autophagy in both solid and blood tumors; however, to our knowledge, the phenomenon has not been reported in breast cancer." (PMID 27421652, 2016). "Targeting mTOR has demonstrated anti tumouractivity in clinical studies; as a result, allosteric inhibitors of mTOR, have beenapproved for the treatment of renal cell carcinoma, pancreatic neuroendocrinetumours and advanced hormone receptor positive, HER2-negative breast cancer." (PMID 27002938, 2016). "This study revealed that total mTOR protein is higher in the breast cancer cells compared to the noncancerous cells, which correlated positively with the level of mTOR activity." (PMID 27748082, 2016). "Moreover, we found that both THBS1- and TNC-activated integrin β1/mTOR signaling played a role in regulating chemotherapy resistance, suggesting that targeting integrin β1/mTOR pathway may be a promising therapeutic strategy to overcome chemotherapy resistance in breast cancer." (PMID 27487140, 2016). "In addition, the synergistic results are consistent with and expand on recent observations of the effect of combining PI3K/mTOR and PARP inhibitors in the treatment of BRCA1-related breast cancer." (PMID 27553366, 2016). "Owing to its target potency and favorable pharmacokinetic properties, MTI-31 inhibited mTOR signaling function in vivo and demonstrated single agent oral antitumor efficacy in tumor models of HER2+/PIK3CAmut breast cancer, PTEN/VHL-null renal cancer and others." (PMID 27563814, 2016). "Our findings revealed that mTOR protein is degraded more rapidly in the noncancerous breast cells compared to the breast cancer cells." (PMID 27748082, 2016). "In particular, we observed that luminal A breast cancers had the highest DRSs while basal breast cancers had the lowest DRSs (P = 5.7E-85, ANOVA), indicating that luminal A and basal breast carcinomas exhibit the lowest and highest PI3K-Akt-mTOR pathway activity, respectively." (PMID 27589846, 2016). "While these observations could indicate a molecular and/or biological link between breast cancer metastatic potential and LAM pathogenesis, the precise role of the identified biomarkers downstream of mTOR signaling remains to be determined." (PMID 26167915, 2015). "The obtained activity scores should reflect the relative activity of AKT signaling in the breast cancer cell lines, and thus we posited that the drug sensitivity values correlating most strongly with the activity scores would be those of PI3K/AKT/mTOR inhibitors." (PMID 25886003, 2015). "Three tumor cell lines (breast cancer MCF-7, colon cancer HCT116 and glioblastoma U87) showed a quick relocation of mTOR to mitochondria after irradiation with a single dose 5 Gy, which was companied with decreased lactate production, increased mitochondrial ATP generation and oxygen consumption." (PMID 25807077, 2015).